BCL2 (BCL2 apoptosis regulator)
Diseases named in the same sentence as BCL2 in open-access papers (continued):
Sharing a sentence is not in itself a finding about the gene and the disease.
tumor (continued). "In order to understand how PFEC induced apoptosis of tumor cells and inhibited cell proliferation, we detected gene expression of cell growth and anti- and pro-apoptosis genes such as Akt, PI3K, Bcl-2, Bcl-xL, Bax, Bid and cell proliferation gene cyclin D1 and PCNA in cells by quantitative PCR." (PMID 25029345, 2014). "In bcl-2 negative patients, univariate analysis showed that Borrmann type, depth of invasion, lymph node metastases, tumor size, tumor location and pathological stage significantly affected prognosis." (PMID 24555747, 2014). "The tumor inhibition rate was not significantly correlated with the expression of antiapoptotic factor Bcl2 (r = −0.095, P >0.05), and apoptotic factors Bax (r = −0.087, P >0.05) and caspase 3 (r = 0.144, P >0.05)." (PMID 24079479, 2013). "Chemotherapy and targeted therapies, including the Bcl-2 inhibitor ABT-737, may induce tumor cell autophagy." (PMID 23452820, 2013). "Moreover, TQ was found to increase p-p38 protein expression in tumor tissues, with down-regulation of XIAP, survivin, Bcl-xL and Bcl-2 anti-apoptotic gene products." (PMID 24098377, 2013). "Our study is significant because we provide evidence that BCL2 is not completely lost in chemoresistant tumor cells post-chemotherapy, and alternate pathways regulate BCL2." (PMID 23671559, 2013). "All 3 had strong tumor nuclear BAF47 staining and all expressed bcl2 and CD99." (PMID 24131748, 2013). "Moderate staining of Bcl-2 was expressed by the peripheral columnar cells of tumor islands and negative in the granular cells." (PMID 23533826, 2013). "As expected, DAPT treatment alone significantly decreased NICD expression (compared with the control group); however, DAPT alone only slight affected Cyclin D1, Bcl2, and Bax gene expression, while SIL had very potent effects on tumor suppression and on the expression of these proteins." (PMID 24386256, 2013). "Western blot analysis of tumor tissue showed no significant treatment effects on the expression of Bcl-2 or Bax proteins, or the ratio of Bax:Bcl-2." (PMID 24152862, 2013). "The expression of Cyclin D1 was associated with tumor size of TSCC (P = 0.023), whereas the expression of Bcl-2 was not statistically significantly associated with any of the clinicopathologic parameters." (PMID 23451060, 2013). "The anti-tumor effect of miR-195 in TSCC could be at least partially via inhibition of Cyclin D1 and Bcl-2 expression." (PMID 23451060, 2013). "Final tumor mass, Bcl-2, Bax, and Cyclin D1 protein levels in tumors were not significantly affected by Se-casein." (PMID 24152862, 2013). "To circumvent this methodological limitation and to rule out the possibility that upregulation of BCL2 is restricted to the pre-invasive stage of tumor development driven by CDH1 inactivation, we evaluated E-cadherin and BCL2 immunoreactivity in LCIS lesions." (PMID 24023670, 2013). "In this more focused tumor series, ILBCs even showed a trend towards a higher frequency of BCL2-negative cases (P = 0.064)." (PMID 24023670, 2013). "Furthermore, GANT-61 inhibits PCSC-containing tumor growth, which is associated with upregulation of TRAIL-R1/DR4 and TRAIL-R2/DR5 expression and downregulation of Gli-1, Gli-2, Bcl-2, and ZEB1 expression in tumor samples obtained from nude mouse xenografts." (PMID 24325450, 2013). "Notably, the morphological analysis demonstrated that TIM-3 was also present on CD68+ macrophages, CD31+ endothelial cells, CK-18+ epithelial cells, as well as on Bcl-2+ and PCNA+ tumor cells." (PMID 24137353, 2013). "Though present, the low frequency of Bcl-2 expression would not be expected to significantly contribute to tumor regression or progression." (PMID 23175106, 2013). "In conclusion, upregulation of BCL2 is not involved in lobular breast carcinogenesis and is unlikely to represent an important determinant of tumor development driven by CDH1 inactivation." (PMID 24023670, 2013).
tumor (continued). "Studies have also shown that BCL2 expression differs by degree of tumor aggressiveness and differentiation, and BCL2 expression has been shown to be very low or absent in higher grade carcinomas compared with lower grade carcinomas." (PMID 23637776, 2013). "In line with this assumption, evaluation of LCIS lesions demonstrated that E-cadherin-negative pre-invasive tumor cells rather exhibit a reduced, but not an increased, BCL2 immunoreactivity, when compared with the adjacent normal epithelium." (PMID 24023670, 2013). "In univariate survival analysis, Bcl2 had no prognostic value, and showed no additional prognostic value to tumor size and histological grade in Cox regression." (PMID 23573235, 2013). "Indeed, Bcl-2 BH3 peptides, which reversed the prooxidant state of Bcl-2-overexpressing tumor cells, sensitized those cells to drug-induced apoptosis." (PMID 22593827, 2012). "Immunostaining showed that the tumor was positive for the Vimentin, Bcl-2 and CD34, and was negative for S-100, desmin, CD68 and α–SMA." (PMID 23148444, 2012). "Another is that in certain tumor cell lines it mediated cell death that is independent of the Bcl-2 status and even stimulated by Bcl-2, although the role of Bcl-2 in Apoptin-induced apoptosis is still a matter of debate." (PMID 22321574, 2012). "Tumor cell lines could be established from all moribund Mock/MYC, MYC/BCL-XL, MYC/BCL-2 and MYC/FLIPL recipient mice." (PMID 22393362, 2012). "The tumor cells were positive for CD99, bcl-2 and focally reactive for CK, EMA in all five cases." (PMID 22862905, 2012). "Bcl-2 expression in OSCC samples was also cytoplasmic and ranged from diffuse expression in low-expressing tumours to strong sporadic expression in high-expressing tumours." (PMID 22852863, 2012). "A higher proportion of HER2 positive tumours were BCL2-low but this was not statistically significant (p = 0.07)." (PMID 23961365, 2012). "As noted already\, our analyses suggest that BCL2 correlates closely with the expression of hormone receptors (both in the whole group of patients and HR-positive tumours) and does not carry an independent information in the data sets." (PMID 22424533, 2012). "Examination of tumor tissue from L-eEF-2K siRNA-treated mice revealed significant cleavage of caspase-9, a positive TUNEL assay (brown staining) and the down-regulation of the anti-apoptotic protein Bcl-2 (Figure." (PMID 22911754, 2012). "Consistent with the immunohistochemical data, Western blot analysis of tumor proteins showed greater increased levels of cleaved caspase-3, cleaved caspase-9, cleaved PARP and Bax, whereas the levels of Bcl-2 and C-IAP1 were significantly decreased in CCR5−/− mice tissues." (PMID 22567084, 2012). "Immunohistochemically, the tumor cells were strongly positive for bcl-2 and CD99, partly positive for CK and EMA, and negative for CD117, CD34, SMA and desmin in all five cases." (PMID 22862905, 2012). "In HR-positive tumours, the aggressiveness of the tumour is best reflected by the combination of Ki67 and ER, rather than Ki67 and BCL2." (PMID 22424533, 2012). "(aka NIX); BCL2/adenovirus E1B 19 kd-interacting protein (BNIP)gene that may function simultaneously with BNIP3 and play arole in tumor suppression." (PMID 22546513, 2012). "HSP-90 promotes survival of tumor cell, induces their growth and metastasis even when there are no growth factors via continued protein translation and cellular proliferation; Its client proteins include: KIT, AKT, CDK4, telomerase, Bcl-2, MMP2 and others." (PMID 23164412, 2012). "Targeting of more than one Bcl-2 molecule clearly increased efficacy and broadened sensitivity among cell lines without loosing tumor specificity." (PMID 22292048, 2012). "This analysis of the experimental data suggests that the primary effect of as-bcl-2 occurs during the first week after injection, a period during which little or no tumor growth is observed." (PMID 23272153, 2012).
tumor (continued). "The tumour cells from the xenograft of the human SCLC cell line NCI-H69 and the human cell line GOT1 stained positively with specific binding for TS1, anti-Ki67, and anti-Bcl-2." (PMID 22214480, 2011). "The tumor cells showed positive immunohistochemical reactions to CD34 and bcl-2." (PMID 22192457, 2011). "With immunohistochemical stains, her tumor cells reacted positive for Bcl-2, CD34, and ki67 and negative for CD10, CD117, S100, and Desmin." (PMID 21819590, 2011). "Untreated controls and regrown tumours were similar in TS1, anti-Ki67, and anti-Bcl-2 staining." (PMID 22214480, 2011). "Finally, CDDO up-regulates p21 and down-regulates cyclin D1 and Bcl-2, thus inducing cell-cycle arrest and apoptosis in MDA-MB-435 tumor cells." (PMID 21524306, 2011). "Here, we show that Over-143 versus Empty xenografts displayed decreased steady-state levels of Bcl-2, and increased caspase-3 activation and PARP processing, suggesting that miR-143 overexpressing xenografts may present higher levels of tumor cell apoptosis." (PMID 21901135, 2011). "When prior available MAL and bcl-2 expression data are included in a multivariate analysis of all clinical and biologic factors, a FOXP3/GrB ratio of 1 or less and tumor cell expression of MAL and bcl-2 all independently predicted poor failure-free survival (FFS)." (PMID 22151904, 2011). "The possibility that Praf2, forming a complex with RTN proteins could be able to potentiate the anti-apoptotic activity of Bcl-2/xL, as shown for RTN3, could also help to explain why an increased Praf2 expression would be selected during tumor formation." (PMID 21203533, 2010). "Furthermore, MA decreased the expression levels of NF-κB-regulated genes, including genes involved in tumor cell proliferation (Cyclin D1, COX-2 and c-Myc), apoptosis (Survivin, Bcl-2, Bcl-xl, XIAP, IAP-1), invasion (MMP-9 and ICAM-1), and angiogenesis (VEGF)." (PMID 20367887, 2010). "The expected model size with the highest performance level consists of 10 of the most robust predictive variables and is comprised of four clinico-pathological variables and six additional proteins: nodal status, tumor size, AURKA, BCL2, age, CD68, HER2, MYBL2, CCNB1 and GSTM1." (PMID 20809974, 2010). "Conversely, reduction of intracellular superoxide sensitized Bcl-2-overexpressing tumor cells to apoptotic stimuli independent of the mitochondria." (PMID 20182539, 2010). "IAPs, the new anti-apoptotic protein families which independent of Bcl-2, are a hot apoptosis research field in recent years, and can play an important role in inhibiting tumor cell growth." (PMID 20525250, 2010). "Another possible reason for the absence of tumor sensitivity to cyclophosphamide after bcl-2 siRNA transfection is that a 50% downregulation of bcl-2 mRNA expression can be insufficient." (PMID 20470373, 2010). "Our data showed that bcl-2 siRNA specifically downregulated the bcl-2 mRNA level by 50% in vitro; however, the bcl-2 siRNA in vivo neither showed any sensitizing effect on RLS tumor nor influenced the tumor growth." (PMID 20470373, 2010). "Tumor cell survival could also be enhanced through activation of anti-apoptotic pathways such as the PI3K/AKT cascade and Bcl2 and Bcl-xL transcription factors." (PMID 21124918, 2010).
tumor (continued). "We show that, in cancers, BCL2 positivity is not simply a surrogate for ER positivity: 14% of BCL2+ tumours were ER− and 31% of BCL2− tumours were ER+." (PMID 20664598, 2010). "A recent review hypothesizes an oncogeneic role of Brn-3a by linking it with Bcl-2/VEGF induction involved in tumor angiogenesis, further implicating the role of this neuronal transcription factor in tumor progression." (PMID 20670407, 2010). "The prognostic impact of BCL2 positivity remained regardless of other tumour characteristics, including tumour size, grade and lymph node status." (PMID 20664598, 2010). "Moreover, we analyzed the levels of mRNA and BCL2 and BCL6 protein in DLBCL tumor tissues by PCR and immunohistochemistry (IHC), respectively." (PMID 20016842, 2009). "Constitutively active Stat-5A (Stat-5A1*6) over-expression efficiently elevates Bcl-2 levels in CD4+ T cells and protects them from tumor-induced death while dominant-negative Stat-5A over-expression fails to do so, indicating the importance of Stat-5A-signaling in CD4+ T cell survival." (PMID 19812686, 2009). "Inhibitory effects of tumor-shed PGE2 were in fact dependent on impairment of IL2Rγc signaling that lead to down regulation of IL2Rγc, reduced phosphorylation of Jak-3 and Stat-5A and decreased expression of pro-survival protein Bcl-2." (PMID 19812686, 2009). "Based on the quantitative RT-PCR experiments presented in this study, a potential source of functional redundancy is Bcl-w, which appears to be expressed at significantly higher levels than Bcl-2, A1, Mcl-1 and Boo in both normal islets and lesional stages of the RIP1-Tag2 tumor pathway." (PMID 19209227, 2009). "Histopathologically, the submucosal tumor uniformly showed a vague, nodular pattern composed of a regular proliferation of CD3-CD10-CD20+CD79a+bcl2+ small lymphoid cells with islands of abortive CD10+Ki67+ germinal centers, without evidence of marginal zone formation or lymphoepithelial lesions." (PMID 19829839, 2009). "Moreover, gene expression levels of ESR1/ERα (P = 0.004), BCL2 (P = 0.003), and FOS (P = 0.01) were significantly lower in grade III (n = 11) than in grade I + II (n = 22) tumor samples." (PMID 18928543, 2008). "YWHAH, or 14-3-3 eta, is a member of the dimeric 14-3-3 family of signal transduction proteins that specifically binds to phosphorylated serine on a variety of signalling molecules, such as Bcl-2, MDMX, and Bax, thereby promoting cell survival and acting antiapoptotic in several tumor cells." (PMID 18959781, 2008). "The activation of IGF1, BCL2 and CCND1 by PTGS2 might be the prolonged legacy of chronic inflammation in early stages of tumor generation." (PMID 17206280, 2007). "A bin is a particular combination of the variables in the model; e.g. in model 1 all individuals with a tumor that is a stage 1 or 2, negative for Bcl-2, and well differentiated belong to one bin (row 1)." (PMID 19455238, 2007). "Patients in whom the primary tumours were both Bcl-2- and Fas-negative showed significantly better responses to immunotherapy in comparison with the remaining group (P=0.0022)." (PMID 17031406, 2006). "HDACIs can also synergise with TRAIL to induce apoptosis by various mechanisms depending on tumour types, such as increased expression of TRAIL-receptors and TRAIL, decrease in c-FLIP, Bcl-xL, XIAP and Bcl-2 expression (or activation), or increased formation of the DISC." (PMID 16930472, 2006). "All primary tumours of CR or PR patients were negative for Bcl-2, whereas among NC+PD patients, 40.6% were positive for Bcl-2 (P=0.0373)." (PMID 17031406, 2006). "We found that patients with metastatic RCC whose primary tumours were both Bcl-2- and Fas-negative demonstrated a better response to immunotherapy in clinical settings." (PMID 17031406, 2006).
tumor (continued). "Bcl-2 staining was positive in 13 of 32 (40.6%) primary tumours from patients with no response (NC+PD) to immunotherapy and in 0 (0%) of eight responders (CR+PR) (P=0.0373)." (PMID 17031406, 2006). "The main findings are that 50% of the radioresistant samples expressed both bcl-2 and bcl-XL, while only 5% of the tumours were negative for both markers." (PMID 15928664, 2005). "Expression of BCL-2 eliminated the apoptotic response, but did not influence the overall response of the tumour as the growth delay was similar for both tumours." (PMID 15452549, 2004). "Crossing the BXB transgenic mice with bcl-2 knockout mice did not change the tumour phenotype, but retarded tumour development mainly due to an increase in the rate of apoptosis." (PMID 14735164, 2004). "In particular, we evaluated TCR ζ and ɛ chains, p56lck, Bcl-2 and Bax expression, FasL and Fas expression on the surface of TIL from surgically obtained tumour samples, and reassessed the same parameters, with the addition of perforin, after TIL were coincubated with IL-2." (PMID 12610520, 2003). "Similar inhibitory effects were also observed in other tumour cells such as HeLa and Jurkat cells stably expressing Bcl-XL, but not Bcl-2." (PMID 12644829, 2003). "Treatment of cultures of nontumorigenic cells with l-deprenyl or clorgyline significantly increased the levels of the protein Bcl-2 following irradiation, but there was no such effect on the already-elevated levels of this protein in the tumour samples." (PMID 14612913, 2003). "In our systematic review with meta-analysis, patients with Bcl-2-positive tumours had significantly better survival than those with Bcl-2-negative tumours." (PMID 12838300, 2003). "Median values were similar for the two tumour types and showed low or absent Fas and Bcl-2 expression, appreciable levels of FasL and very high levels of Bax expression." (PMID 12610520, 2003). "Multiple alterations contribute to carcinogenesis, and tumours that counter apoptosis by overexpressing Bcl-2 and/or BAG-1 might represent one class of tumours." (PMID 12373595, 2002). "Among the remaining 114 patients whose tumour cells did not express bcl-2 protein, 75 (66%) were responders (P=0.001)." (PMID 12454767, 2002). "Those patients who simultaneously expressed BAX and BCL-2 had a longer progression-free and overall survival compared to patients whose tumours did not express BCL-2 (P = 0.05 and 0.015 respectively)." (PMID 11720475, 2001). "In contrast there was a positive relationship between markers of angiogenesis and bcl-2 expression in prolactinomas, GH-secreting tumours and non-recurrent functionless tumours with higher levels of bcl-2 expression being found in the more vascular tumours." (PMID 10780524, 2000). "With respect to Bcl-2, 51% of tumours were completely negative, 32% displayed weak and 15% moderate staining; only 3% showed strong positive staining." (PMID 9667656, 1998). "From a series of 441 premenopausal, lymphnode-negative breast cancer patients, a subset of 49 tumours was selected in which immunostaining for the 26-kDa isoform of Bcl-2 was either absent (n = 23) or very high (n = 26)." (PMID 9514059, 1998). "It was shown that Bcl-2 expression is not related to patients' age, tumour size and type or lymph node status, but an inverse relationship was observed between Bcl-2 and tumour grade (P < 0.0001)." (PMID 9252201, 1997).